PBK (PDZ binding kinase)
Diseases named in the same sentence as PBK in open-access papers (continued):
Sharing a sentence is not in itself a finding about the gene and the disease.
Ewing sarcoma (7 papers, 2010 to 2026). A small round cell tumor that lacks morphologic, immunohistochemical, and electron microscopic evidence of neuroectodermal differentiation. "PBK, one of 10 hub immune-related genes signature, was determined to exhibit independent prognostic significance for Ewing’s sarcoma." (PMID 35065633, 2022). "Another study reported that PBK/TOPK expression was decreased due to EWS–FLI1 inhibition, which promoted a reduction in the cell proliferation rate and prevented the cells of Ewing sarcoma from growing and coalescing." (PMID 30286126, 2018).
kidney cancer (7 papers, 2016 to 2025). Primary or metastatic malignant neoplasm involving the kidney. "The forest plot indicated that PBK/TOPK expression was remarkably associated with RCC (p < 0.001) and can be used as an independent prognostic factor in kidney cancer." (PMID 35546143, 2022). "Two other specific PBK inhibitors, OTS514 and OTS964, could significantly decrease PBK expression and inhibit tumor proliferation in lung and kidney cancer and acute myeloid leukemia." (PMID 30778048, 2019).
liver cancer (7 papers, 2016 to 2024). An epithelial or non-epithelial malignant neoplasm that arises from the liver. "It interacts significantly with PDZ-binding kinase (PBK) and influences the prognosis and immune infiltration of liver cancer." (PMID 38410514, 2024). "In recent years, studies have shown that PBK/TOPK is expressed in a variety of tumors, such as lung, stomach, and liver cancers." (PMID 36171591, 2022). "PBK had also been revealed to be a metastasis regulator in liver cancer." (PMID 34055036, 2021).
lymph node metastasis (7 papers, 2016 to 2022). "The same authors demonstrated in a patient series (n=48) with gastric adenocarcinoma, that high nuclear PBK protein expression was associated with an invasive phenotype, higher stage, deep invasion and lymph node metastasis." (PMID 28978135, 2017). "Nuclear PBK expression was associated with increased gastric adenocarcinoma invasiveness, including higher stage (P = 0.002), depth of invasion (P = 0.017), and lymph node metastasis (P = 0.001), similar to the PSMB nuclear expression results." (PMID 26894977, 2016). "Strong nuclear expression of PSMB8 and PBK significantly correlated with increased depth of invasion and lymph node metastasis, respectively." (PMID 26894977, 2016). "According to the Spearman correlation analysis, histological grade (P = 0.015), TNM stages (P = 0.013), lymph node metastasis (P = 0.002), low ER (P = 0.005), low PR (P = 0.027), HER-2 (P = 0.037), and Ki-67 (P < 0.001) were associated with PBK/TOPK protein expression." (PMID 36171591, 2022). "According to our analysis, when the histology and TNM stage are higher, with lymph node metastasis and HER-2 positivity, the positive expression of PBK/TOPK is more prominent, and the prognosis is relatively poor." (PMID 36171591, 2022). "Clinicopathological characteristic analysis showed that PBK expression was correlated with lymph node metastasis but not with other features." (PMID 30778048, 2019).
bladder cancer (6 papers, 2019 to 2021). "Previous study indicated that PBK/TOPK might be an immunotherapy target in bladder cancer." (PMID 34859049, 2021).
myeloma (6 papers, 2006 to 2024). "PBK has also been reported to enhance the malignant potential of cells, such as by promoting cellular proliferation of tumor cells, and its expression in malignant tumors such as multiple myeloma is associated with patient survival." (PMID 35115926, 2021). "Indeed, we demonstrated that inhibition of PBK reduced myeloma cell growth and enhanced lenalidomide and bortezomib activity in the IMiD‐resistant cell lines JJN3 and XG1LenRes." (PMID 36051067, 2022). "Our study not only demonstrates PBK as a promising novel target of FHND004 to inhibit MM cell proliferation, but also expands the EGFR kinase-independent direction for developing anti-myeloma therapy." (PMID 38460944, 2024). "Our group successfully inhibited the growth of multiple myeloma and CRC cells using OTS514, a specific PBK inhibitor." (PMID 35115926, 2021).
non-small cell lung carcinoma (6 papers, 2016 to 2026). A group of at least three distinct histological types of lung cancer, including non-small cell squamous cell carcinoma, adenocarcinoma, and large cell carcinoma. "To address this discrepancy, we analyzed the correlation between PBK/TOPK expression and the degree of immune cell infiltration in non-small cell lung cancer (NSCLC)." (PMID 35203508, 2022). "Among them, DLGAP5 could physically interact with PBK, TOP2A, and CDK1, and all mitosis-associated proteins correlated with poor prognosis for non-small cell lung cancer patients." (PMID 32426332, 2020). "Non-small cell lung cancer patients with high PBK/TOPK expression levels also had a poorer overall and recurrence survival when compared to patients with lower PBK/TOPK expression." (PMID 27347940, 2016).
oral cancer (6 papers, 2016 to 2026). "In conclusion, our study findings demonstrated that PBK/TOPK is specifically expressed in oral cancer and that increased expression is associated with good prognosis in some particular patients." (PMID 27347940, 2016). "We verified the role of PBK/TOPK in the prognosis of oral cancer patients by recruiting 287 patients with primary tumors." (PMID 27347940, 2016). "PBK/TOPK expression was measured by immunohistochemical staining of samples from 287 patients with oral cancer." (PMID 27347940, 2016). "Further molecular studies are also needed to provide a more in-depth picture regarding the function of PBK/TOPK in oral cancer." (PMID 27347940, 2016). "However, in other studies, PBK/TOPK overexpression has shown a favorable prognosis in colon, bile duct, esophagus, and oral carcinomas." (PMID 35203508, 2022). "Moreover, PBK was also overexpressed in oral cancer, and is known to be a favorable prognostic indicator for oral cancer." (PMID 33403046, 2021). "Our results suggest that PBK/TOPK expression is enhanced in oral cancer." (PMID 27347940, 2016). "The present study is the first to report PBK/TOPK expression in oral cancer." (PMID 27347940, 2016). "We sought further evidence for a prognostic role of PBK/TOPK expression in oral cancer patients." (PMID 27347940, 2016). "We evaluated the expression of PBK/TOPK (PDZ-binding kinase/T-LAK cell-originated protein kinase) and its prognostic significance in oral cancer." (PMID 27347940, 2016). "High PBK/TOPK expression, either alone or in subgroups according to clinicopathological features, may serve as a favorable prognostic marker for patients with oral cancer." (PMID 27347940, 2016).
gastric adenocarcinoma (5 papers, 2016 to 2024). "Increased nuclear PBK expression was associated with a poor prognosis in gastric adenocarcinoma ((−), 72.3 ± 1.2; (+), 66.2 ± 3.4; (++), 53.1 ± 9.2; P = 0.002)." (PMID 26894977, 2016). "For example, increased expression of PBK has been linked to poor prognosis in patients with ovarian serous cystadenocarcinoma (OV), esophageal carcinoma (ESCA), and stomach adenocarcinoma (STAD)." (PMID 34859058, 2021). "Nuclear/cytoplasmic PBK expression in gastric adenocarcinoma tumor cells was classified as follows: - (306/385, 79.5%), + (67/385, 17.40%), and ++ cytoplasmic expression (12/385, 3.1%); - (234/385, 60.8%), + (117/285, 30.4%), and ++ nuclear expression (34/385, 8.8%)." (PMID 26894977, 2016). "PBK expression was identified in cytoplasm and nuclei of gastric adenocarcinoma cells." (PMID 26894977, 2016).
metastatic disease (5 papers, 2010 to 2021). "Future studies in this direction are needed to shed more light on the significance of nuclear localization of PBK/TOPK, for example, the mechanism of action leading to up-regulation of PBK/TOPK-responsive gene targets that contribute to the development of aggressive, metastatic disease." (PMID 25909225, 2015). "In our study, PBK expression in HCC was gradually increased from nontumorous, primary to metastatic tumor." (PMID 28525379, 2017).
thyroid cancer (5 papers, 2007 to 2026). "PBK methylation level was a prognostic marker in thyroid carcinoma (THCA)." (PMID 34859058, 2021). "The involvement of PBK has not previously been observed in thyroid cancer, but previous data have demonstrated that the constitutive activation of effectors along the MAPK/ERK signalling pathway display a key role in the genesis and progression of a substantial proportion of papillary tumours." (PMID 17406368, 2007).
Cerebral ischemia (4 papers, 2018 to 2025). Restriction of arterial blood supply to the brain associated with insufficient oxygenation to support the metabolic requirements of the tissue. "As PBK/TOPK is well-known to be upregulated in a variety of actively proliferating tissues, its specific roles in myocardial, renal, and cerebral ischemia have drawn our interest." (PMID 33670114, 2021). "Activated PBK/TOPK conferred neuroprotection against focal cerebral ischemia/reperfusion injury by its antioxidative effects, in part through activation of the extracellular signal-regulated kinase pathway." (PMID 33670114, 2021). "Moreover, studies have revealed a role of PBK/TOPK in ischemic injury, including cardiac, renal, and cerebral ischemia, and have demonstrated that it mediates the protective effects of ischemic postconditioning against ischemia." (PMID 33670114, 2021).
metastatic prostate carcinoma (4 papers, 2015 to 2022). A carcinoma that arises from the prostate gland and has spread to other anatomic sites. "It demonstrates a tightly associated sub-network of the meiotic cell cycle with strictly meiosis-specific (i.e., HORMAD1, MND1, SMC1B) genes and includes CT genes such as TTK and PBK (known also for metastatic prostate carcinoma)." (PMID 36499258, 2022).
psoriasis (4 papers, 2022 to 2026). An autoimmune condition characterized by red, well-delineated plaques with silvery scales that are usually on the extensor surfaces and scalp. "In our study, PTG1, HMMR, PBK, FEN1, DEPDC1 may be some psoriasis-related genes in IL-17A treating of psoriasis." (PMID 37029373, 2023).
renal carcinoma (4 papers, 2022 to 2025). A carcinoma arising from the epithelium of the renal parenchyma or the renal pelvis. "ERK2 can phosphorylate TOPK/PBK to promote tumorigenesis and participate in sorafenib resistance of renal cancer; ERK2-induced PDHE1α phosphorylation and subcellular translocation promote tumor immune escape." (PMID 36966163, 2023).
acute myeloid leukemia (3 papers, 2015 to 2023). Acute myeloid leukemia (AML) is a group of neoplasms arising from precursor cells committed to the myeloid cell-line differentiation. "The down-regulation of Nrf2 induces the decrease of cdc2 and cyclin B protein expression through the down-regulation of PBK/TOPK, which leads to cell cycle arrest and apoptosis of acute myeloid leukemia (AML) cells." (PMID 37810967, 2023).
brain tumor (3 papers, 2015 to 2023). "To assess PBK expression in GBM, we first investigated the mRNA and protein levels of PBK in GIC cultures derived from human brain tumor and in normal samples." (PMID 26081429, 2015). "Furthermore, PBK inhibition has been studied as a strategy to treat many cancers including brain tumors." (PMID 37341142, 2023).
colon adenocarcinoma (3 papers, 2022 to 2023). "Compared with tumor adjacent tissues, EEF1A2, PBK and TIMP1 showed significant upregulation in colon adenocarcinoma, while ATP2A3, CDC25C, MMP3 and NAT1 showed significant downregulation." (PMID 37626132, 2023).
COVID-19 (3 papers, 2021 to 2025). A disease caused by infection with severe acute respiratory syndrome coronavirus 2. "The GSE167028 and GSE150392 datasets were subjected to a recent bioinformatic analysis, which unveiled six critical genes (CDK1, KIF20A, PBK, KIF2C, CDC20, and UBE2C) associated with COVID-19 myocarditis." (PMID 40230577, 2025). "Eventually, 6 genes (CDK1, KIF20A, PBK, KIF2C, CDC20, UBE2C) were identified by CytoHubba plug-in of Cytoscape as critical genes of COVID-19 Myocarditis for future study." (PMID 35749386, 2022). "Based on 5 algorithms of the CytoHubba plug-in, six genes (CDK1, KIF20A, PBK, KIF2C, CDC20, UBE2C) were confirmed as critical genes related to COVID-19 Myocarditis." (PMID 35749386, 2022). "It is worth highlighting that critical genes (CDK1, KIF20A, PBK, KIF2C, CDC20, UBE2C) may be potential biomarkers and treatment targets of COVID-19 Myocarditis for future study." (PMID 35749386, 2022). "Based on topological algorithms (i.e., degree), in this study, CDK1, KIF20A, PBK, KIF2C, CDC20, and UBE2C were identified as critical genes that may be potential biomarkers for COVID-19 Myocarditis." (PMID 35749386, 2022).
endometrial cancer (3 papers, 2017 to 2021). Primary or metastatic malignant neoplasm involving the endometrium (mucous membrane that lines the endometrial cavity). "We selected the six hub genes (GTSE1, BIRC5, AURKA, PBK, KNSTRN, and PSMB10) and AKT1 to evaluate gene expression values in endometrial cancer using IHC." (PMID 31781484, 2019). "Tumor volume, SUVmax and SUVmean were significantly higher in lesions with high PBK protein expression (p≤0.03 for all) and PBK mRNA expression was significantly anti-correlated to ADC value in low grade endometrial cancer and CAH (p=0.03, data not shown)." (PMID 28978135, 2017).
neuroblastoma (3 papers, 2020 to 2023). Neuroblastoma (NB) is the most common solid, extracranial childhood tumor. "LIN28B and its downstream target PDZ‐binding kinase (PBK, also known as TOPK) are oncogenic in neuroblastoma and promote growth and self‐renewal via the LIN28B–let‐7–PBK axis." (PMID 37341142, 2023). "We went on to additionally define PBK as a direct transcriptional target of MYCN, thus linking PBK to two neuroblastoma oncogenes, LIN28B and MYCN." (PMID 32923517, 2020). "Given the overlap between LIN28B and PBK in mediating self-renewal and migration, we hypothesize that both LIN28B and PBK promote neuroblastoma metastasis." (PMID 32923517, 2020). "While our findings show that PBK lies downstream of both LIN28B and MYCN, and the functions of PBK mimic those of LIN28B in vitro, whether PBK sculpts neuroblastoma metastasis in the in vivo setting is unknown." (PMID 32923517, 2020).
osteosarcoma (3 papers, 2021 to 2025). A usually aggressive malignant bone-forming mesenchymal neoplasm, predominantly affecting adolescents and young adults. "The overexpressed kinases in osteosarcoma, liposarcoma, and leiomyosarcoma are mainly serine/threonine kinases (BUB1, CKD4, HUNK, LKKK1, NEK2, PBK, PLK1, and PLK4), whereas TTK has a dual role (Tyrosine and serine/threonine kinase) and only MELK presents tyrosine phosphorylation activity." (PMID 40723917, 2025).
serous ovarian carcinoma (3 papers, 2019 to 2020). "PBK promotes the metastasis of serous ovarian carcinoma and confers cisplatin resistance." (PMID 30987661, 2019).
liver cirrhosis (2 papers, 2021 to 2022). "Two diagnostic models including SOCS2, LCAT, FTCD, KRT17, PBK, and CBX2 expression were proved to accurately separate HCC from normal and liver cirrhosis samples in this study." (PMID 36159831, 2022).
medulloblastoma (2 papers, 2023 to 2024). A malignant, invasive embryonal neoplasm arising from the cerebellum. "In summary, the findings indicated that the tumor microenvironment-responsive nanocomposite HPAA/RVG/PBK-siRNA selectively inhibited PBK expression in Daoy medulloblastoma cells, showcasing potential applicability in medulloblastoma therapy." (PMID 39628686, 2024). "This work aimed to demonstrate the therapeutic effects of tumor microenvironment-responsive nanotherapeutic drugs targeting PSD95/Discs-large/ZO-1 domain (PDZ)-binding-kinase (PBK) in medulloblastoma Daoy and ONS-76 cells." (PMID 39628686, 2024). "Overexpression of LIN28B in Group 3 medulloblastoma cells promotes the upregulation of PBK and other oncogenes via inhibition of the microRNA let‐7." (PMID 37341142, 2023). "Taken together, our data support the hypothesis that LIN28B and its downstream target PBK are important regulators of Group 3 medulloblastoma cell proliferation and that targeting the LIN28B–PBK axis with pharmacologic therapy is plausible." (PMID 37341142, 2023).
oral squamous cell carcinoma (2 papers, 2016 to 2021). "In this study, our aim was to evaluate the expression of PBK/TOPK and its clinical significance in oral squamous cell carcinoma." (PMID 27347940, 2016). "However, the potential for an association between PBK/TOPK expression and oral squamous cell carcinoma has never been addressed." (PMID 27347940, 2016).
pituitary tumor (2 papers, 2021 to 2024). A benign or malignant neoplasm affecting the pituitary gland. "Through rigorous functional validations, we observed that both GGH and PBK significantly inhibited pituitary tumor cell apoptosis and enhanced cell proliferation." (PMID 38167466, 2024). "Notably, further transwell experiments demonstrated that PBK also significantly increased the migration of GH3 pituitary tumor cells, implying the potential role in facilitating tumor cell invasiveness." (PMID 38167466, 2024).
sarcoma (2 papers, 2021 to 2024). A usually aggressive malignant neoplasm of the soft tissue or bone. "We performed immunohistochemistry (IHC) on DDLS and WDLS to confirm protein expression of TTK, PBK and SPA17, as well as CTAs commonly expressed in sarcoma including NY-ESO-1 (included in Nanostring panel as CTAG1B), SSX2 and MAGE-A3, some of which that have been targeted by adoptive cell therapy." (PMID 38755218, 2024).
triple-negative breast carcinoma (2 papers, 2021 to 2022). An invasive breast carcinoma which is negative for expression of estrogen receptor (ER), progesterone receptor (PR), and human epidermal growth factor receptor 2 (HER2). "In terms of the molecular types, high expression of PBK/TOPK was observed in 9.10% (3/33), 41.88% (31/74), 55.1% (27/49), and 60.00% (18/30) of patients with luminal A type, luminal B type, HER-2(+) type, and triple negative breast cancer (TNBC), respectively (P < 0.001)." (PMID 36171591, 2022).
brain cancer (1 paper, 2022). A primary or metastatic malignant neoplasm affecting the brain. "Previous studies have reported that high PBK/TOPK expression is correlated with a poor prognosis in colon, gastric, lung, and brain cancers." (PMID 35203508, 2022).
breast tumours (1 paper, 2009). "Therefore, PBK is also a potential therapeutic target, as it encodes a mitotic protein, member of MAPK kinases family, which was found to be over-expressed in haematological and breast tumours, and in PDTC cell lines." (PMID 19809427, 2009).
cervical intraepithelial neoplasia (1 paper, 2017). "Interestingly, in cervical intraepithelial neoplasia (CIN), PBK protein expression has been demonstrated to incrementally increase in higher grade premalignant lesions and further to cancer and increasing PBK protein expression level is linked to more aggressive tumors." (PMID 28978135, 2017).
Cirrhosis (1 paper, 2023). A chronic disorder of the liver in which liver tissue becomes scarred and is partially replaced by regenerative nodules and fibrotic tissue resulting in loss of liver function. "They found that RRM2, cyclin-dependent kinase 1 (CDK1), PDZ-binding kinase (PBK), abnormal spindle homolog, and microcephaly-associated Drosophila (ASPM) were key genes for HCC transformation from cirrhosis." (PMID 36768940, 2023).
colitis (1 paper, 2024). Inflammation of the colon. "A PPI network based on DEGs was constructed using STRING, and a highly interconnected cluster was identified as a potential functional molecular complex of colitis, including 8 hub genes, that is, NDC80, PBK, CEP55, RRM2, ASPM, NCAPG, TOP2A, and CDKN." (PMID 38661103, 2024).